EGFR (epidermal growth factor receptor)
Diseases named in the same sentence as EGFR in open-access papers (continued):
Sharing a sentence is not in itself a finding about the gene and the disease.
tumor (continued). "Although the effect of EGFR-TKIs in cancer signaling and clinical outcome are well established, the potential of blocking EGFR signaling as a means to facilitate tumor targeting by anti-tumor immune effector cells has not been thoroughly investigated." (PMID 27685624, 2016). "EGFR activation plays an important role in malignant cell proliferation, angiogenesis, metastasis and inhibition of apoptosis, and PD1 plays a critical role in tumor immune evasion." (PMID 27329726, 2016). "Although we cannot be certain that we had enough tumor volume with average 3 aspirations, our low discordance rate suggests that LN sampling using EBUS-TBNA is a reasonable approach for tissue acquisition and EGFR testing of NSCLC." (PMID 27685950, 2016). "We defined EGFR gene amplification as an EGFR/CEP7 ratio > 2.0 in 20 tumor nuclei and polysomy-7 were regarded as negative for gene amplification." (PMID 27438149, 2016). "Our data, in a genetically controlled background, suggest that the level of EGFR activation, not just the total protein levels, is an important determinant of tumor cell phenotype." (PMID 27738329, 2016). "No significant epidermal growth factor receptor (EGFR/HER1) expression was detected in the MMTV-NIC tumours, so it was not possible to assess effects on EGFR activation (results not shown)." (PMID 26721874, 2016). "Its expression and the sequential PGE2 production could upregulate EGFR, PI3K, and ERK1/2 signaling to induce angiogenesis, cell proliferation, invasion, and metastasis of tumor cells." (PMID 26672764, 2016). "The tumor also contained detectable EGFR, with weak/moderate membrane and cytoplasmic signal but no nuclear positivity." (PMID 27200287, 2016). "For example, EGFR inhibitors can up-regulate the expression of MHC-II and CIITA compartment on head and neck squamous cell carcinoma cell line and augment antigen specific anti-tumor T cell responses." (PMID 27467256, 2016). "Platelet-derived growth factor (PDGF) and signaling via its receptors plays a crucial role in tumor cell proliferation and thus may represent an attractive target besides VEGF/EGFR-based antibody therapies." (PMID 27626684, 2016). "The plasma c-Met levels in the tissue c-Met-positive group were 672.57 ± 239.58 ng/ml (95% CI: 318.91 - 1232.67) before EGFR-TKI treatment, 546.15 ± 159.54 ng/ml (95% CI: 360.33 - 971.51) at the time of the best tumor response, and 986.42 ± 578.36 ng/ml (95% CI: 483.36 - 2208.06) with PD." (PMID 27213587, 2016). "Preclinical studies of ficlatuzumab monotherapy for non-small cell lung cancer (NSCLC), which has a similar genetic profile to HNSCC, resulted in reduced tumor growth and decreased levels of phospho-MET, phospho-ERK, and phospho-Akt, but a concurrent increase in phospho-EGFR." (PMID 27669306, 2016). "In contrast, no accumulation of 99mTc-D10 in MDA-MB-231 tumours characterized by a very low expression of EGFR was observed." (PMID 26912069, 2016). "Furthermore, when anti-EGFR combined with anti-VEGF treatment, the tumor growth and angiogenesis were significantly suppressed compared with other groups." (PMID 27729020, 2016). "It would be attractive to further validate these findings in prospective serial rebiopsy study in EGFR-mutant patients under EGFR-TKI therapy, including the early time-window in the midst of tumor response (1st week to 1-2 months post-therapy), using comprehensive transcriptomic profiling analysis." (PMID 27852038, 2016). "Despite one simple HCA near a transplant tumor after TTx, neither the EGFR nor the TGFα were upregulated in hormonal induced alterations of hepatocytes after TTx." (PMID 27669229, 2016).
tumor (continued). "Furthermore, both PDXs and the original tumors exhibited conserved genomic DNA alterations including both EGFR amplification and PTEN deletion as well as EGFR, p-EGFR, PTEN, p-SRC, and p-AKT expression correlating with that of the parental tumor." (PMID 27438149, 2016). "Responders to neoadjuvant 5-fluorouracil-based chemoradiotherapy (patients with significant tumor regression) showed significantly lower EGFR (ERBB1) gene expression levels than nonresponders (patients with insignificant tumor regression)." (PMID 27610130, 2016). "All of these studies found that targeting EGFR or MET alone did not produce significant tumor regression." (PMID 27259997, 2016). "In contrast to the pro-tumorigenic effects of EGFR and GABAAR signaling, membrane expression mediated through autophagy-related proteins also results in the expression of receptors that may inhibit tumor progression, for example through KOR signaling." (PMID 27933272, 2016). "In cohort 2, high PODXL expression was an independent prognostic factor in patients with tumours displaying low but not high EGFR expression (unadjusted HR 2.02; 95 % CI 1.02–4.02) and adjusted HR 2.59; 95 % CI 1.26–5.31)." (PMID 27160084, 2016). "Indeed a modest activation of the EGFR signaling pathway has been demonstrated also in EGFR-WT NSCLC, promoting cancer cells proliferation, motility and invasiveness, stimulating tumor angiogenesis and inhibiting apoptosis processes." (PMID 26993607, 2016). "Additionally, the vascular endothelial growth factor A (VEGF-A) and its receptor VEGFR-1/2 were interacted to affect to tube formation of tumor cells by TGF-β1, at same time, EGF/EGFR also has similar activity." (PMID 27613831, 2016). "EGFR and HER2 genes were co-amplified in eight tumours (3.6 %)." (PMID 27387915, 2016). "One of the reasons why EGFR and HER2 are good targets could be that the signals through EGFR and HER2 are indispensable for growth of tumor cells." (PMID 27834817, 2016). "While residual estrogen receptor activity and tumor cell proliferation were detected at relapse, no meaningful increases were found in EGFR/HER2/MAPK activity." (PMID 26178788, 2016). "Because EGFR activation may trigger the initial step of IL10 synthesis, its secretion out of cancer cells to develop the tumor microenvironment would benefit cancer development." (PMID 26956044, 2016). "Previous studies have suggested that ZKSCAN3 directly or indirectly regulates the expression of various genes, such as CCND1, CCND2, EGFR, IGF-2, integrin-β4, NF-κB, and VEGF, all of which are known to involve tumorigenesis, tumor progression, and/or metastasis." (PMID 27447553, 2016). "Namely, most patients who achieved stable disease as best response developed RAS mutations, whereas patients with partial response preferentially showed EGFR ECD mutations, either with or without RAS, in their tumours." (PMID 27929064, 2016). "Up-front tumor RAS testing—rather than solely KRAS exon 2 testing—is critical for patients with mCRC, as RAS mutations predict a lack of response to anti-EGFR therapy." (PMID 26573425, 2016). "Finally, we evaluated the effect of EGFR and ROCK silencing on tumor cell viability in vitro and growth in vivo." (PMID 27374095, 2016). "The purpose of this study is to investigate an association between cytologic tumor markers and FDG uptake with EGFR mutation status in non-small cell lung cancer (NSCLC)." (PMID 26979333, 2016). "It is currently unknown whether synergism of EGFR/KRAS and FLCN LOH accelerates tumor progression in the lung." (PMID 26974543, 2016). "Consistent to the PCNA data, the proliferation rate in the GPRC5A-expressed human tumour cells did not significantly change although the EGFR level was markedly reduced." (PMID 27273304, 2016). "In addition, BD-138T parental tumor tissues showed significantly activated SRC and AKT, suggesting these pathways as druggable targets specific to concomitantly EGFR-amplified and PTEN-deleted MIBCs." (PMID 27438149, 2016).
tumor (continued). "Moreover, EGFR knockout in HCT116 cells dramatically reduced the M2 macrophage population and tumor growth." (PMID 27683110, 2016). "Our finding of a positive effect of gemcitabine only in cases with low EGFR expression has to our knowledge not been shown in these tumour types before." (PMID 27070783, 2016). "Finally, because of the limitation in the availability of EGFR-TKI resistant LAC tumors from relapsed patients, only a small number of samples were tested, and only 4 primary tumor cells can be adapted to stable culture and drug test." (PMID 27015549, 2016). "EGFR expression in the resected tissues was not correlated with tumor proliferation (p = 0.154 for Ki67 analysis) or tumor stages (p = 0.473); however, there was a correlation with differentiation (p = 0.015)." (PMID 27399694, 2016). "Previous studies demonstrated that EGFR and ALK genes could induce PD-L1 expression to facilitate evasion of the host anti-tumour immune response, suggesting an active role for these genes in remodelling the immune microenvironment." (PMID 27342566, 2016). "Cells from CLH21, a relapsed LAC tumor harboring EGFR-T790M mutation, were not sensitive to Cyclopamine or HHIP overexpression, presumably due to the T790M-driven EGFR activation that maintained cell survival." (PMID 27015549, 2016). "We used the nCounter expression assay (NanoString®) to measure the expression of EGFR, erb-B2 receptor tyrosine kinase 2 (ERBB2), ERBB3, ERBB4, and estrogen receptor 1 (ESR1) genes using mRNA extracted from paraffin-embedded tumor tissues from 203 patients diagnosed with TNBC." (PMID 26907936, 2016). "The combination of HER2, CAIX, GLUT1, EGFR, IGF1-R and MET could detect 45.5 % of tumours, including basal/triple negative and HER2-driven ductal cancer." (PMID 26860296, 2016). "EGFR+ tumour xenografts from mice treated with C-MMAE showed increased accumulation in G2/M by pS10 Histone H3 staining compared with cetuximab, verifying delivery of active MMAE to tumours." (PMID 27698471, 2016). "In contrast to that found after intrathoracic PDT at 150 mW/cm, illumination at 75 mW/cm did not increase EGFR activation in the proliferating areas of tumor nodules with an incomplete response to PDT." (PMID 26784170, 2016). "A supra additive effect in inhibition of clonogenic survival, apoptosis enhancement and tumor growth suppression was observed by simultaneously combination treatment with celecoxib (COX-2I), erlotinib (EGFR inhibitor) and IR in the HNSCC and phase I clinical study." (PMID 27923354, 2016). "In further subgroup analyses, no relevant differences were reported for any of the studied efficacy endpoints in patients whose tumours were positive for EGFR expression compared with those whose tumours were negative." (PMID 26766738, 2016). "A total of 16 (43.2%) of 37 patients had tumours that were positive for EGFR expression by IHC; 21 (56.8%) had tumours that were EGFR negative." (PMID 26766738, 2016). "In this model, we found that, although erlotinib blocked EGFR activity, tumor growth was not affected." (PMID 27612423, 2016). "In spite of inhibition of EGFR phosphorylation, weekly administration of erlotinib failed to delay tumor growth (p = 0.97), which is consistent with the previous reports." (PMID 27612423, 2016). "In the tumor tissues originated from the LV-miR-128 transfected PC9, we found that the gefitinib treatment significantly inhibited the phosphorylation of the entire EGFR/PI3K/AKT signaling pathway." (PMID 27690301, 2016). "Univariate analysis showed that gender (male), ECOG-PS ≥ 2, current or former smokers, tumor stage IV, non-adenocarcinoma histology, wild-type EGFR status, neutrophilia and NLR ≥ 3.7 were significantly associated with worse OS." (PMID 27029035, 2016).
tumor (continued). "In tumour tissues from the BGC-823-xenografted nude mice treated with DT-13-TPT combination, the positive areas for TUNEL, cleaved caspase-3 and NM IIA were increased, while the positive areas for p-ERK1/2, EGFR and Cav-1 were reduced." (PMID 27105508, 2016). "To fill this gap in knowledge, we analyzed nuclear VDR expression in tumor cores from lifetime never-smokers that had corresponding DNA available for targeted sequencing of the EGFR gene." (PMID 26654942, 2016). "Earlier tumor stages, non-lymph metastasis and EGFR negative expression were significantly related to a longer progression free survival (PFS) (p = 0.006, p = 0.001 and p = 0.040)." (PMID 27399694, 2016). "T790M EGFR clinical samples also showed decreased expression of these key enzymes; increasing intra-tumoural GSH levels with a small-molecule GST inhibitor re-sensitised resistant tumours to erlotinib in mice." (PMID 27721983, 2016). "Cetuximab is a promising agent that targets epidermal growth factor receptor (EGFR) and has shown an impressive ability to improve the tumor response and increase progression-free survival (PFS) and overall survival (OS) among patients with all RAS wild-type mCRC." (PMID 26863631, 2016). "AT13387 treatment resulted in a strong reduction in the target protein HSP90 and client protein EGFR in both tumour models as shown by the H-scoring method, while no significant changes in CD44v6 expression were observed." (PMID 26627081, 2016). "The results of our study indicate that combining FAK inhibition with erlotinib more effectively reduces EGFR wild-type NSCLC cell viability in vitro and xenograft tumor growth in vivo than either drug treatment alone, with particular efficacy in the A549 cell type." (PMID 26962872, 2016). "A recent meta-analysis of 33 studies showed that although HNSCC patients with high EGFR expression had a poorer OS regardless of the type of treatment, a large heterogeneity was reported, mainly related to tumor site and IHC scoring system." (PMID 27556186, 2016). "The ORR was 62.5% (95% CI 35.4–84.8) among patients with EGFR-expressing tumours and 66.7% (95% CI 43.0–85.4) among those whose tumours were negative for EGFR expression." (PMID 26766738, 2016). "Additionally, epidermal growth factor, an important ligand for EGFR, also drives VEGF expression, and an overactive VEGF pathway plays a role in tumor resistance to treatment with EGFR inhibitors." (PMID 27245053, 2016). "EGFR driven NSCLC tumors, in particular, have been demonstrated to secrete increased local concentrations of tumor promoting cytokines including IL-6, GCSF, and GM-CSF among others in the immediate tumor microenvironment." (PMID 27866514, 2016). "In the tumor sample of patient A, we observed positive staining for Tid1-L, negative staining (−) for EGFR and hnRANP A1, and weakly positive staining (+/−) for hnRNP A2." (PMID 26919236, 2016). "Analysis for EGFR mutations and EML4-ALK translocation was not possible due to insufficient tumor material for molecular testing." (PMID 26959886, 2016). "Due to tumor heterogeneity, some cells in a tumor may express IGF1R, whereas other cells may express EGFR, and yet other cells may express insulin receptors, and all these cells may generate PI3K-AKT pro-survival signals." (PMID 27460078, 2016). "In summary, these results suggest that miR-218-5p possesses tumor-suppressing activity and may repress NSCLC development by negatively regulating EGFR expression." (PMID 27057632, 2016). "The average plasma c-Met levels in the tissue c-Met-negative group were 602.72 ± 135.59 ng/ml (95% CI: 403.42 - 873.86) before EGFR-TKI treatment, 531.47 ± 128.85 ng/ml (95% CI: 333.44 - 755.92) at the time of the best tumor response, and 601.55 ± 120.94 ng/ml (95% CI: 386.24 - 881.84) with PD." (PMID 27213587, 2016). "Furthermore, we have shown that A3 was able to re-sensitize EGFR-TKI resistant NSCLC cells, leading to inhibition of tumor growth in xenograft models." (PMID 26862736, 2016).
tumor (continued). "In addition, the overexpression of miR‐134 inhibited EGFR‐related signaling and suppressed NSCLC cells proliferation by inducing cell cycle arrest and/or apoptosis, suggesting that miR‐134 functions as a tumour suppressor in NSCLC." (PMID 27241841, 2016). "Studies demonstrated that not only the EGFR B cell epitopes consisted of residues from EGFR contacting sites with EGF, but also the combination treatments of peptide vaccines exhibited significant anti-tumor effects in vitro or in vivo." (PMID 27659529, 2016). "However, EGFR knockout in HCT116 cells dramatically reduced Ana-1-induced tumor growth; the tumor promotion efficiency of Ana-1 cells decreased from 2.7-fold with HCT116 cells to 1.3-fold with HCT116 KO-EGFR cells." (PMID 27683110, 2016). "We also presented the first in vivo proof-of-concept evidence to support the efficacy of combination BCL-2/BCL-xL BH3 mimetic with EGFR TKI in circumventing early adaptive drug resistance and thus resulting in durable tumor response in EGFR-mutant NSCLC precision therapy." (PMID 27852038, 2016). "Our findings taken together may have many clinical implications for NSCLC patients receiving EGFR-targeted therapy and undergoing 18F-FDG PET/CT to monitor tumor response." (PMID 27726115, 2016). "Notably, the combination of EGFR-CAR NK-92 cells with oHSV-1 resulted in more efficient killing of MDA-MB-231 tumor cells and significantly longer survival of tumor-bearing mice when compared to monotherapies." (PMID 27050072, 2016). "A total of 46% of patients exhibited EGFR immunoreactivity independent of tumor size, disease grade, and histological grade (P = 0.49, P = 0.40, and P = 0.12, respectively)." (PMID 27230280, 2016). "While there was no protocol-mandated proactive management of skin toxicity in the present study, it is now recommended for patients receiving EGFR inhibitors." (PMID 27764839, 2016). "In our study, ECOG-PS ≥ 2, IV tumor stage, non-adenocarcinoma histology, EGFR wild-type status and NLR were predictors of worse OS, whilst tumor stage IV, wild-type EGFR status and NLR ≥ 3.7 were independent prognostic factors for worse PFS." (PMID 27029035, 2016). "As opposed to current anti-EGFR therapies, which inhibit EGFR activity per se, we exploit EGFR expression and activation as the Achilles’ heel of the tumor." (PMID 27598772, 2016). "In this study, we further revealed the molecular details of how a tumour suppressor and the signal transduction pathways of JAK and EGFR coordinately regulate stem cell competition and stem cell tumour formation by manipulating integrin expression in one type of stem cells." (PMID 26792023, 2016). "Among the predicted conserved miRNAs with favourable mirSVR scores, we focused on those miRNAs that function as tumour suppressors but that have not been identified to regulate EGFR." (PMID 27241841, 2016). "Analysis of DNA extracted from 2008 (pre-trial) tissue showed that the tumor harbored wild-type EGFR, and a PIK3CA mutation was detected in plasma, but not tumor DNA." (PMID 27200287, 2016). "MDA-MB-231 tumours with a very low expression of EGFR showed no detectable uptake of the anti-EGFR nanobody 99mTc-D10 in vivo." (PMID 26912069, 2016). "In the tumor sample of patient B, we observed negative staining (−) for Tid1-L and positive staining (+) for hnRNP A1, hnRNP A2, and EGFR." (PMID 26919236, 2016). "In this regard, short-term culturing of GBM-derived primary cells as three-dimensional tumor spheres under stem cell conditions rather than as adherent monolayers has indicated that EGFR amplification can be maintained in vitro." (PMID 26136784, 2015). "Lapatinib, a clinically approved ERBB2/EGFR inhibitor, counteracts BCAR4-driven tumor cell growth." (PMID 26317614, 2015). "Erlotinib exerts antitumor activity through inhibition of EGFR tyrosine kinase, but its antitumor activity is not correlated with the level of EGFR expression by tumor cells." (PMID 26053020, 2015).